U3 (Small nucleolar RNA U3 )
Synonyms: LOC124903595
Gene: Small nucleolar RNA gene on chromosome 15 (36,852,640 to 36,852,859, forward strand). Ensembl gene ENSG00000212511.
Gene Ontology:
Biological process: RNA processing
Cellular component: nucleolus
Homologues: Orthologues: chimpanzee U3 (99% identical), macaque U3 (94% identical), rat LOC120095492 (74% identical), rabbit U3 (57% identical). Paralogues in human: U3 (79% identical), SNORD3G (77% identical), U3 (75% identical), SNORD3P1 (75% identical), U3 (73% identical), U3 (72% identical), SNORD3H (72% identical), U3 (71% identical), SNORD3D (71% identical), SNORD3E (71% identical), U3 (70% identical), U3 (69% identical), and 11 more.